IL6 (interleukin 6)
Diseases named in the same sentence as IL6 in open-access papers (continued):
Sharing a sentence is not in itself a finding about the gene and the disease.
tumor (continued). "In addition, PRL-3 in cancer cells could upregulate the secretion of IL-6 and IL-8 through MAPK signals acting on tumor-associated macrophages." (PMID 36286020, 2022). "Thus, tumor-infiltrating M2-TAMs promote the NED process by activating downstream IL-6 signaling." (PMID 35938167, 2022). "As a response, some soluble mediators such as IL-6 (interleukin- 6) could be selectively released from BMSCs as well, and in turn, enhancing the proliferation capacity of tumor cells by stimulating the STAT3 (signal transducer and activator of transcription 3) signaling pathway." (PMID 35255950, 2022). "Indeed, IL-6 signalling is pleiotropic and highly complex, and alongside its well-known tumour-promoting effects, it paradoxically promotes effector T cell priming within lymph nodes and subsequent trafficking to tumour sites, which in turn suppresses tumour development." (PMID 35359426, 2022). "TAMs can interpret tumor cells directly and lead to chemoresistance through the production of colony-stimulating factors (CSF)-1, increasing protease activity, inducing stemness of cancer cells through IL-6-mediated activation of STAT3 signals, and inducing enzymes involved in drug inactivation." (PMID 35658848, 2022). "Considering that IL-6 plays a crucial role in regulating and activating myeloid-derived suppressor cells (MDSCs) and that MDSCs can harbor anti-tumor immunity, it is speculated that clarithromycin may have immunomodulatory effects by decreasing IL-6 and subsequently suppressing MDSCs." (PMID 35205754, 2022). "Therefore, targeting tumor-derived IL-6 with pharmacological inhibitors may negate chemoresistance pathways in docetaxel-treated MSL TNBCs." (PMID 35260569, 2022). "Thirdly, tumor-associated macrophages (TAMs) within the TME can become activated by cancer cells via an unspecified mechanism, presumably related to Snail stabilization and the epithelial-to-mesenchymal transition (EMT) that triggers the secretion of IL-1β and IL-6." (PMID 36613445, 2022). "Importantly, the pathway of IL6ST was directly correlated with SMG1 expression in most tumor types in line with previous observations and indicating that IL-6 axis could be an inducer of SMG1." (PMID 36443756, 2022). "In a retrospective study of GOG-0218, high plasma IL6 levels were found to be a clinical biomarker for predicting the efficacy of bevacizumab, suggesting that differences in plasma IL6 levels may reflect differences in tumor biology in OCCC." (PMID 35565252, 2022). "Furthermore, prior work from our group has revealed that CAF-derived IL-6 engages in tumor-permissive crosstalk by activating STAT3 signaling within tumor cells, and that heightened CAF-tumor cell IL-6/STAT-3 signaling crosstalk is a central mediator of chemoresistance in PDAC." (PMID 36107485, 2022). "Cancer-derived EVs may also activate the tumor-associated macrophages and consequently activate the secretion of vascular endothelial growth factor (VEGF), IL-6, miRNAs, and transcription factors, which together promote angiogenesis, contributing to tumor progression." (PMID 35386696, 2022). "Considering the key role of the circCUL2-induced cascade in the activation of the NF-κB/IL6 signaling pathway, targeting circCUL2 could potentially convert iCAFs into a more myofibroblastic state that has been previously suggested to inhibit tumor progression." (PMID 35189958, 2022). "Current findings may be explained by a Treg subset of CD4+ T cells having cycled from cancer tissue into blood; alternatively, elevated levels of circulating cytokines such as IL-6, IL-10, and TGFβ may explain the tumor-suppressive profile in these blood samples." (PMID 35158758, 2022). "As such, the improved chemosensitivity associated with NLR attenuation in our preclinical models suggest that combining chemotherapy with therapeutic strategies to mitigate neutrophil-stromal-tumor cell IL-1β/IL-6/STAT-3 signaling in PDAC patients may be advantageous." (PMID 36107485, 2022).
tumor (continued). "Cluster 8 and cluster 12, which have high-risk scores and mostly appeared in the middle stages of LUAD (12w and 18w), showed more cellular response (such as IL2, IL6), and the abilities were lost with tumor progression, which could be related to the tumor progression." (PMID 36387251, 2022). "However, IL-6 secretion was relatively low in both SCs and tumor cells." (PMID 36465391, 2022). "IL-6 is associated with MA formation in OC patients being involved in the upregulation of VEGF expression which leads to increased vascular permeability, promotes tumor growth, mediates cytokine release, and is associated with cachexia (extreme weight loss and muscle wasting) in cancer patients." (PMID 36142615, 2022). "Moreover, bevacizumab may be more effective for patients with the mesenchymal transcriptomic subtype of OCCC and high tumor IL6 expression." (PMID 35565252, 2022). "These may suggest that the association between the IL-6/IL-10 mRNA expression ratio and the degree of tumor malignancy is not a strong linear positive correlation." (PMID 36371539, 2022). "In addition, common cytokines such as IFN-gamma and IL-6 may contribute to urine cytotoxicity, and could play an important role in tumor micro-environment." (PMID 36260626, 2022). "However, the downregulation of ANXA2 by CuO NPs might prevent tumor progression and angiogenesis via inhibition of macrophage activation and secretion of IL-1, IL-6, and TNF-α." (PMID 36362054, 2022). "Thus, the over-secretion of IL-6 in TME, not only by the tumor cells themselves but also by cancer-associated macrophages, fibroblasts, adipocytes, or mesenchymal stem cells, creates favorable conditions for tumor development and metastasis." (PMID 35454797, 2022). "In addition, tumor cells can also produce IL-6 to establish an autocrine signaling axis." (PMID 35729402, 2022). "Furthermore, IDO1 induces tumor angiogenesis in vivo by regulating the IFN-γ/IL-6 balance." (PMID 35681736, 2022). "Upon tumor cell encounter, CAR-T cells release different pro-inflammatory cytokines, such as TNF-α, IFN-ɣ, IL-1, and granulocyte-macrophage colony-stimulating factor (GM-CSF), that leads to macrophage recruitment and activation, causing a dangerous cytokine storm involving IL-6 and GM-CSF." (PMID 35694446, 2022). "To determine whether the anti-tumor effect of the active ingredients of YFBP is associated with the regulation of the expression of the inflammatory mediator, we assessed the gene expression of TNFα, IL-1β, and IL-6." (PMID 36353478, 2022). "Therefore, we hypothesized that IL-6/IL-6R might play a role in regulating tumor suppressor genes in GBMs cells through a common downstream molecular mechanism." (PMID 36106122, 2022). "Immune cells in the tumor microenvironment, including TAM, tumor-infiltrating lymphocytes, and tumor-associated neutrophils, are considered to be capable of secreting large amounts of circulating factors such as IL-6 and IL-1 to promote the malignant progression of cachexia." (PMID 35740622, 2022). "Cytokines IL-6 and IL-8 have been demonstrated to synergistically regulate a range of characteristics of cancer metastasis which were found to cooperatively regulate cancer cell proliferation, migration and the seeding of circulating tumour cells in various cancer cell types." (PMID 35484352, 2022). "Furthermore, we also explore whether the inhibition of Sox4 can affect the tumor-bearing mice mediated by IL-6 in vivo." (PMID 35513871, 2022). "Furthermore, IL-6 signaling also induces the polarization of immature myeloid cells to macrophages or MDSCs instead of antigen-presenting DCs, which in turn contributes to tumor progression." (PMID 36627890, 2022). "Based on preliminary data and published reports supporting a role for cytokine and estrogen signaling crosstalk, we sought to test the hypothesis that there is an interplay between IL6/LIF cytokine signaling in the tumor microenvironment and estrogen signaling." (PMID 36230597, 2022).
tumor (continued). "Similarly, knockdown of IL6R in tumor cells suppressed both IL-6/JAK/STAT3 and TGFβ signaling, and suppressed EVsMMA-MRC5-induced EMT marker expression, drug resistance, and invasion and migration, suggesting that IL-6R activation functions upstream of TGFβ pathway signaling in this context." (PMID 36266345, 2022). "Although the role of signal transducers and activators of transcription (STAT3) in cachexia due to the association of circulating IL-6 and muscle wasting has been extensively demonstrated, the effect of resistance training on STAT3 in mediating muscle atrophy in tumor-bearing mice is unknown." (PMID 35847939, 2022). "In contrast, most features associated with 4T1 tumour growth were significantly different from normal levels in Nil animals, with G-CSF level and neutrophil count being >10-fold higher, PD-L1+ myeloid cell count being ~2-fold higher, and both CXCL13 and IL-6 levels being ~<2-fold higher than normal." (PMID 35226704, 2022). "Interestingly, TNF-α was upregulated while IL-6 was downregulated in the tumor microenvironment." (PMID 35418151, 2022). "TAMs may accelerate tumor cell proliferation by secreting protumor cytokines including IL‐6." (PMID 35132816, 2022). "Since CD4+ Th2 cells and Th2 cytokines such as interleukin-4 (IL-4), IL-5, IL-6, IL10 and IL13 were thought to be associated with immunosuppressive contexture and tumor-promoting effects, we believed that LMNB1 could be considered as a biomarker of immunosuppressive microenvironment." (PMID 35241075, 2022). "Notably, the amount of IL-6 was significantly reduced in N6L-treated tumours compared to controls." (PMID 36077801, 2022). "Additionally, an elevated concentration of IL6 in serum was associated with a negative prognosis of the tumor in patients with different cancer types." (PMID 36354566, 2022). "It has been reported that miR-100-5p could inhibit IL-6 and TLR4 mRNA gene expression in follicular dendritic cells during germinal center reactions, suppress inflammatory activation of microglia and promote tumor-associated macrophage M2 phenotype." (PMID 35874782, 2022). "Similarly, IL-6 can support tumor proliferation and metastatic dissemination." (PMID 36551577, 2022). "Similarly, the IL6-JAK-STAT3 signaling pathway may promote tumor cell proliferation, invasion, and metastasis and suppress immune response." (PMID 35832194, 2022). "Our results complement that IL-6 and IL-8 are similarly aberrant in AA expression in hematological non-neoplastic diseases and may have a role in discriminating bacterial or co-fungal infections because only IL-6 had a solid sensitivity to bacterial lung infection in our results." (PMID 36319826, 2022). "However, cytokines released by tumor cells, such as G-CSF, IL-1β, IL-6, or tumor necrosis factor (TNF), have been proposed to prolong neutrophil lifespan, indicating that neutrophils may have a significant impact on cancer." (PMID 35784290, 2022). "Additionally, IL-6 plays a role in the recruitment of immune cells within the tumor microenvironment, thereby stimulating the production of other pro-inflammatory cytokines, including IL-1β, IL-8, and TNFα, thus providing a link between the inflammatory process and tumor progression." (PMID 35053592, 2022). "Furthermore, high expression of IL-6 in serum and tumor tissue, as well as marked expression of interleukin-17 (IL-17) in peritumoral cells negatively correlated with overall survival (OS) and disease-free survival (DFS) in patients who underwent surgical resection of iCCA." (PMID 35205774, 2022). "In tumor microenvironment, cytokines played a major role in the regulation of the cellular responses between tumor cells and immune cells, for example, TGFβ, IL-10 and IL-6 could dampen the anti-tumor response of NK cells by suppressing activity and promote subsequent tumor evasion and progression." (PMID 36126190, 2022).
tumor (continued). "With this clever design, researchers can achieve effective tumour eradication without causing severe safety issues in tumour‐bearing mice, as indicated by substantial attenuation of B cell aplasia and reduced production of interleukin 6, a proinflammatory cytokine regarded as the culprit for CRS." (PMID 36101937, 2022). "Moreover, tumor cells could secrete various molecules to attract MDSCs into TME like GM-CSF and IL-6, in turn, MDSCs induce the mutations of tumor cells and express some proteins like SA100A8/9 to avoid immune surveillance." (PMID 36246629, 2022). "Thus, IL-6/JAK/STAT3 may directly inhibit tumor cell growth or indirectly enhance the antitumor immune response effects of immune checkpoint inhibitors." (PMID 35799780, 2022). "Besides IL-6, various immunosuppressive cytokines have been identified to play significant roles in shaping a protumoral immune landscape and subsequently driving tumor growth." (PMID 36230502, 2022). "This phenomenon could be related to the specific tumor signature since IL-6 deficiency did not affect esophageal tumorigenesis." (PMID 36405719, 2022). "Furthermore, pathways directly related to the immune response against tumor cells such as leukocyte activation involved in inflammatory response, regulation of leukocyte activation, interleukin-6 production were under-represented in CDK2AP1 gene set enrichment analysis." (PMID 36362115, 2022). "In addition to macrophages, monocytic or polymorphonuclear myeloid-derived suppressor cells (MDSC) derived from early myeloid precursors can also contribute to T cell suppression when conditioned by tumor-derived suppressive cytokines, such as IL-6, VEGF, and TGF-β." (PMID 35207374, 2022). "Notably, N6L treatment decreased IL-6 levels both in tumour tissues and in serum." (PMID 36077801, 2022). "Thus, IL-6 plays an important regulatory role for tumour initiation in CRC." (PMID 35793807, 2022). "This might be due to a decrease in IL-6 secretion during the process of tumour progression." (PMID 35022523, 2022). "Furthermore, Inhibition of autophagy in macrophages reprogrammed pro-tumor M2-like TAMs to a tumor-suppressing M1 phenotype that exerted anti-tumor effects by regulating not only NF-κB p65 protein homeostasis but also an IL-6-pSTAT3-miR-155-3p-autophagy-pSTAT3 positive feedback loop." (PMID 36300110, 2022). "IL-6 gene expression is elevated in the heart of tumor-bearing mice, which are characterized by impaired cardiac function and increased fibrosis, hinting to the possible involvement of cardiac fibroblasts in tumor-induced cardiac dysfunction in rodents and humans." (PMID 35967380, 2022). "Besides, application of cytokine antagonists, such as targeting the tumor-promoting cytokine IL6, might also improve therapeutic outcomes by triggering ICD in cancer patients." (PMID 36497433, 2022). "While counteracting tumor EV-decoy function might improve immunotherapy efficacy the same EV property might be advantageous when used therapeutically to neutralize the activity of inflammatory molecules such as IL-6 or TNFα." (PMID 35563789, 2022). "Therefore, resistance to cediranib in the 30200 model could be partially overcome by inhibiting IL6 signaling; combination treatment increased survival, reduced tumor burden, and angiogenesis." (PMID 35313341, 2022). "Again, we observed that p62 expression decreased while LC3-II increased over LC3-I in tumor spheroids exposed to RV for either ten days or only the first five days, indicating that autophagy flux was stimulated, and this effect contrasted the inhibitory action of IL-6." (PMID 35565270, 2022). "However, we cannot exclude that in vivo Notch activation may promote MDSCs, through other mechanism/s, such as those based on ligand/receptor interactions, and that other cell subsets may participate in releasing IL-6 in the tumor microenvironment." (PMID 35444651, 2022).
tumor (continued). "In addition, IL-6 can promote platelet production, and activated platelets can act as chemotactic agents for tumor cells, promoting the formation of metastatic lesions and increasing the level of circulating tumor cells." (PMID 35634419, 2022). "In addition to the direct promoting effects on tumor cells, IL-6 could induce CRC progression by modulating the tumor immune microenvironment." (PMID 36362062, 2022). "Moreover, IL6 also can regulate tumor progression through other pathways." (PMID 35692503, 2022). "Furthermore, our data potentially identifies a population of TNBC patients that may benefit from supplementing chemotherapy with tocilizumab to eliminate autocrine tumor production of IL-6." (PMID 35260569, 2022). "Additionally, IL-6 supports angiogenesis and tumor evasion of immune surveillance." (PMID 35954428, 2022). "Furthermore, interleukin (IL)-6 and IL-10 signaling have tumor-promoting functions." (PMID 36092724, 2022). "Interestingly, one study reported that WMP attenuated CAC by regulating the balance between “tumor-promoting bacteria” and “tumor-suppressing bacteria” and the NF-κB/IL-6/STAT3 pathway in mice, highlighting that WMP was a potential effective chemo-preventive drug." (PMID 35927991, 2022). "However, there were anti-tumor lncRNAs negatively regulating IL-6/STAT3 signaling." (PMID 35222443, 2022). "However, recent reports demonstrate that the immunomodulatory functions of succinate are more complex, as it can suppress the secretion of the inflammatory mediators IL-6, tumours TNF-α and NO, as well as inhibit IL-1b mRNA transcription in inflammatory macrophages." (PMID 35216253, 2022). "In addition, Il-6 plays a role in a tumor development and in several cellular processes." (PMID 35567250, 2022). "There have been reports of the synthesis of IL-6 by various cell types, including immune cells, endothelial cells, skeletal and smooth muscle cells, thyroid cells, fibroblasts, mesangial cells, keratinocytes, microglial cells, astrocytes, certain tumor cells, and islet cells." (PMID 36510592, 2022). "However, the depletion of MMP9 make the tumour cells more invasive and metastatic, a process that is facilitated by the presence of CD11b+ inflammatory monocytes expressing pro-invasive cathepsin B and the secretion of interleukin-6." (PMID 35216069, 2022). "To explore whether IL-6 could mediate inter-clonal communication within a heterogeneous IBC tumor in vitro, we investigated whether supernatant from high IL-6-producing SUM149 cells could induce activation of the JAK-STAT3 signaling pathway and downstream effects in IL-6R positive SUM190 cells." (PMID 35565421, 2022). "On one hand, a wealth of evidence supports a role for cytokines, such as IL-6, in promoting tumour progression by increasing proliferation, survival, and invasion of cancer cells, thus it could be deduced that reducing IL-6 through physical activity may help to avert cancer." (PMID 35359426, 2022). "Importantly,the most promising bioconjugates of LAS significantlyreduced the secretion of interleukin 6 (IL-6) in the cancer cellswhen compared to the control, which may result in the weakening ofthe IL-6 tumor-promoting effects." (PMID 35071884, 2022). "However, immunohistochemistry analysis of tumor cells with specific antibodies for IL-6 and VEGF revealed few positive immunostainings of these two targets, and there were no statistical differences between the two groups, untreated tumors and AM11095 treated tumors." (PMID 36564457, 2022). "Therefore, targeting the IL-6/JAK/STAT3 pathway in patients with ONB might provide therapeutic benefit by directly suppressing tumor cell proliferation and restoring antitumor immunity, as already demonstrated in several other histotypes." (PMID 34064009, 2021). "Hence, it is supported that IL-6 may act directly on the tumor with a subsequent worse RCC prognosis, both in an autocrine and paracrine manner." (PMID 32621022, 2021).